PPP2R1A (protein phosphatase 2 scaffold subunit Aalpha)
Diseases named in the same sentence as PPP2R1A in open-access papers (continued):
Sharing a sentence is not in itself a finding about the gene and the disease.
cancer (continued). "However, we have observed that the method of using shRNAs against Ppp2r1a in cancer cell lines had better anti-cancer effects on mouse tumours models than the method of systemic administration of LB100." (PMID 34911954, 2021). "Since targeting PP2A can enhance ICB response through modification of both tumours-intrinsic and extrinsic factors, the in vivo anti-cancer immunotherapy effect of systemic administration of LB-100 should be better than that of Ppp2r1a gene knockdown in mouse cancer cells." (PMID 34911954, 2021). "In addition, PPP2R1A and PPP2R2A alterations have been associated with whole genome doubling in a pan-cancer study of TCGA data." (PMID 28039471, 2017). "The modulation of the PPP2R1A-RAB dimer abundance may play a key role in the functional inactivation of PP2A leading to cancer onset and progression." (PMID 27611305, 2016). "Anyway, all these implicated the SNPs in PPP2R1A and PPP2R5E are involved in tumorgenesis, suggesting that the variants in PPP2R1A and PPP2R5E may be valuable biomarkers to predict risk of cancer." (PMID 24204789, 2013). "Therefore, the present study is the first attempt to determine whether PPP2R1A has an effect on cancer using different cancer cell lines and healthy fibroblast cells and propolis, whose phenolic content we determined due to its heterogeneity." (PMID 39850502, 2025). "Non-recurrent, cancer-specific mutations (n = 28 genes across 11 cancers) predominantly correlated with high telomerase activity, with notable exceptions including PPP2R1A in UCS, HRAS, and GTF2I in THYM and SMAD4 in PAAD." (PMID 41321994, 2025). "Specifically, the downregulation of PCYT2 in cancer cells not only decreased PE level but also attenuated the interaction between PEBP1 and PPP2R1A." (PMID 39531326, 2024). "Compared to MSS cancers, MSI cancers had increased expression of CIP2A and decreased expression of PPP2R1A." (PMID 34911954, 2021). "Most known cancer genes have been found through primary cytogenetic analyses, although sequencing of cancer genomes has revealed new cancer genes including BRAF, EGFR, ERBB2, PIK3CA, PPP2R1A, and JAK2." (PMID 34298667, 2021). "Surprisingly, only eight identified genes (CCND1, CDK6, CDKN2A, KDM5A, MDM2, MLL3, PPP2R1A, and RB1) are shared by UniCovEx and CovEx, and they are all NCG cancer genes." (PMID 30828525, 2019). "Screening the top 200 genes with monotonic expression against the Cancer Gene Census yielded a completely different set of six genes: HSP90AB1, ALDH2, ESR1, PPP2R1A, HIST1H4I, SEPT5." (PMID 31277598, 2019). "However, distinct PPP2R1A missense mutations might affect B subunit binding and PP2A activity in a slightly different way, thereby, in part, contributing to a different tumor biology in type I and II ECs as well as other cancers." (PMID 31214504, 2019). "It was observed that propolis treatment did not change the levels of PPP2R1A in healthy cells but increased them in cancer cells." (PMID 39850502, 2025). "Moreover, disruption of α2 integrin, MAP3K1, MAPK11, PPP2R1A, and NHE1-mediated ECM internalisation significantly impaired cancer cell migration and invasion in 2D and 3D culture systems." (PMID 39666682, 2024). "Nonetheless, whether PPP2R1A is downstream of WNK1 in angiogenesis and cancer remains obscure." (PMID 36292952, 2022). "Furthermore, one study showed that recurrently mutated cancer driver genes, such as KRAS, PIK3CA, PPP2R1A, and ARID1A, are also present in endometriosis without cancer association." (PMID 34202354, 2021). "Functions of the remaining genes - including CSNK1E, FOSL1, PPP2R1A, and PPARD – are widely reported as being relevant to cancer (if not specifically NSCLC) biology." (PMID 33027769, 2020).
cancer (continued). "Another subgroup of PPIs presumably perturbed by cancers is characterized by negative or near-zero r-values in cancers and positive r-values of gene co-expression in conditionally normal tissues, for example, C1orf131/EIF3L, C19orf53/APEX1, C1orf198/PPP2R1A and C1orf198/ARHGEF1." (PMID 37373333, 2023).
tumor (49 papers, 2013 to 2025). "The study also examined the association between PPP2R1A expression and clinicopathological features, such as tumor stage and lymph node involvement, highlighting its prognostic significance in early-stage LUAD." (PMID 41409293, 2025). "For the second patient, who experienced a confirmed response, the tumor had evidence of a mutation in PPP2R1A and low copy number gain of CCNE1 (estimated <6 copies)." (PMID 40678577, 2025). "A four-gene panel consisting of ARID1A, CTNNB1, FBXW7 and PPP2R1A was used to investigate mutations in gynaecologic tumour tissue." (PMID 36982928, 2023). "We unambiguously showed that these tumor-associated mutations inactivate PPP2R1A with respect to migration persistence and to the differentiation of polarized acini in Matrigel." (PMID 37322026, 2023). "The current study also supports this theory, in which murine ppp2r1a-deficient tumours exhibit enhanced CD8+ T cell infiltration and reduced Foxp3+ Treg infiltration." (PMID 34911954, 2021). "Because SEIC is the pre-invasive precursor of USC, indicating that mutations in PPP2R1A occur early during tumor progression of USC." (PMID 27272709, 2016). "The overexpression of WT PPP2R1A promoted tumor growth while W257G mutation increased cell migration through the SRC-JNK-c-Jun pathway." (PMID 27272709, 2016). "Furthermore, we explored the genetic interactions and immune cell infiltration patterns related to PPP2R1A, revealing its involvement in critical pathways associated with tumor progression." (PMID 41409293, 2025). "Additionally, the few PPP2R1A mutations found in endometrioid ECs are mostly correlated with high-grade endometrioid EC, suggesting PPP2R1A mutations are associated with aggressiveness of the tumour and poor patient outcome." (PMID 30104481, 2018). "Through bioinformatic analysis, coimmunoprecipitation assay, loss-of-function, and rescue experiment, PPP2R1A, which is a component of the tumor suppressor PP2A, could bind to NET and affect its protein level, dephosphorylate pAkt, and influence its activity of regulating VEGF gene expression." (PMID 37156838, 2023). "As a core scaffold subunit of the PP2A complex and a regulator of migration persistence, the function of PPP2R1A has traditionally been thought to inhibit pro-tumor signaling pathways (PI3K/AKT and MAPK) through dephosphorylation." (PMID 41409293, 2025). "Our immune infiltration analysis revealed a more complex and unexpected relationship between PPP2R1A and the tumor immune microenvironment." (PMID 41409293, 2025). "Mechanistically, mutations in the PPP2R1A gene induce a strong interferon gamma response in tumor cells, which enhances infiltration of activated CD8+ T cells into the tumor." (PMID 40737443, 2025). "Alterations in PPP2R1A, often involving missense mutations, impair the assembly or stability of the PP2A complex, compromising its tumor-suppressive functions." (PMID 40072110, 2025). "To investigate PPP2R1A’s immunomodulatory potential, we assessed its co-expression patterns with tumor-infiltrating immune cell signatures across the LUAD." (PMID 41409293, 2025). "KEGG pathway enrichment analysis revealed that key pathways involving PPP2R1A-associated genes include ‘cell cycle,’ ‘cell senescence,’ and ‘PPAR signaling pathway,’ suggesting that PPP2R1A promotes tumor progression by regulating proliferation and metabolism." (PMID 41409293, 2025).
tumor (continued). "It has been shown that common genetic alterations in PPP2R1A (which encodes the inhibition of PP2A activity), affecting up to 40%, promote malignant transformation in the tumor-suppressing heterotrimeric PP2A Aα subtype." (PMID 39850502, 2025). "Analysis using the TIMER online tool revealed that PPP2R1A expression is significantly elevated in various tumor samples, including STAD." (PMID 40251453, 2025). "PPP2R1A has potential oncogenic properties in the progression of GC, and knocking down the expression of PPP2R1A can inhibit the tumor progression of GC cells." (PMID 40251453, 2025). "Next, we employed TIMER2 to analyze the correlation between PPP2R1A gene expression patterns and immune infiltration levels across various tumor types in the TCGA." (PMID 41409293, 2025). "We employed multiplex immunohistochemical (mIHC) and RT-qPCR to explore the protein and mRNA expression of PPP2R1A among tumor and adjacent tissues of LUAD patients." (PMID 38654331, 2024). "In light of these insights, we initially focused on PPP2R1A, and found that PPP2R1A was significantly upregulated in LUAD tumor tissues through both TCGA database and clinical samples." (PMID 38654331, 2024). "To sum up, we reveal the WNK1 downstream effectors involved in tumor-induced angiogenesis and tumor migration, and PPP2R1A acts as a tumor suppressor." (PMID 36292952, 2022). "Increased levels of CD8+ tumour-infiltrating T cells were found in tumours formed by CT26 cells with Ppp2r1a knockdown compared to those formed by WT CT26 cells." (PMID 34911954, 2021). "We then analysed the repertoire of T cell receptor (TCR) rearrangements in mice that received either WT CT26 or CT26 with Ppp2r1a knockdown tumour cells." (PMID 34911954, 2021). "The results showed that PPP2R1A expression level accompanied with tumor grade or gender significantly correlated with overall survival." (PMID 32754603, 2020). "The high degree score of PPP2R1A indicates the probable involvement of PP2A in tumor cell responses to cyano enone-containing triterpenoids, which is consistent with published data." (PMID 31523389, 2019). "The second most mutated gene in type II ECs turned out to be PPP2R1A, encoding the Aα subunit of the Ser/Thr-specific PP2A phosphatase, a known tumour suppressor." (PMID 30104481, 2018). "In this study, we found that phosphatase activity by PP2A was strongly repressed in this tumor; that is, the PPP2R1A expression was suppressed and that expression of SET, a PP2A suppressor, was upregulated by PAX3-FOXO1 in ARMS." (PMID 29861864, 2018). "The silencing of PPP2R1A significantly increased the cell growth of all four ARMS cells, suggesting that PPP2R1A still has a tumor suppressive function in ARMS cells; however, the native expression of PPP2R1A was low in the presence of PAX3-FOXO1." (PMID 29861864, 2018). "The recent identification of the SDL interaction between the mitotic checkpoint protein MAD2 and PPP2R1A provides a possible avenue to overcome tumor heterogeneity." (PMID 27557495, 2016). "PPP2R1A (E370X), SETD2 (I1608V), SMAD4 (G382T), and AR splicing site mutations were determined to be potential metastatic tumor-specific mutations." (PMID 27023146, 2016). "Consistent with in vitro results, both SKOV3 and HEC-251 cells overexpressing PPP2R1A-WT showed a dramatic increase in tumor growth." (PMID 27272709, 2016). "This could provide a foundation for future therapeutic strategies targeting PPP2R1A to modulate tumor growth and immune responses in LUAD patients." (PMID 41409293, 2025). "Additionally, we investigated the relationship between PPP2R1A expression levels and the tumor immune microenvironment." (PMID 41409293, 2025).
tumor (continued). "This inverse relationship with critical Treg effector molecules suggests that high PPP2R1A expression may be associated with an altered, or potentially dysfunctional, Treg compartment within the LUAD tumor microenvironment." (PMID 41409293, 2025). "However, in wild-type samples, PPP2R1A expression was significantly higher in tumor tissues compared to normal tissues (P < 0.001)." (PMID 40251453, 2025). "Experimental validation using techniques such as immunohistochemistry (IHC), flow cytometry, or single-cell RNA sequencing (scRNA-seq) on LUAD patient tissues is needed to confirm these findings and precisely map PPP2R1A expression within specific cellular compartments of the tumor microenvironment." (PMID 41409293, 2025). "Further exploration of PPP2R1A in LUAD could reveal novel mechanisms of tumor progression and therapeutic vulnerabilities." (PMID 41409293, 2025). "PPP2R1A expression correlated with advanced N stage and tumor stage." (PMID 41409293, 2025). "Furthermore, the scatter plot in illustrates the correlation between PPP2R1A mRNA and protein levels across tumor and adjacent normal tissues." (PMID 41409293, 2025). "Based on the GO enrichment result for the ‘snRNA metabolic process’, PPP2R1A may indirectly influence the alternative splicing of tumor-related genes by regulating the activity of splicing factors." (PMID 41409293, 2025). "To further examine whether PPP2R1A drives tumor formation and drug resistance, we performed PPP2R1A-overexpression and PPP2R1A-knockdown experiments using lentiviral-based overexpression and knockdown approaches." (PMID 38654331, 2024). "Therefore, we assessed the effect of Ppp2r1a knockdown on tumour growth and response to antibodies against PD-1 (anti-PD1) in the MSS CRC cell line, CT26." (PMID 34911954, 2021). "Bioinformatics analyses revealed an expansion of the 20 more-represented TCR rearrangements in mice receiving CT26 with Ppp2r1a knockdown tumour cells, suggesting that Ppp2r1a knockdown in mouse MSS CRC triggers neoantigen generation and sensitises them to ICB-mediated anti-tumour activity." (PMID 34911954, 2021). "Expression of PPP2R1A significantly correlated with tumor stage, tumor grade as well as gender." (PMID 32754603, 2020). "In addition, overexpression of PPP2R1A-WT increased cell proliferation in vitro and tumor growth in vivo." (PMID 27272709, 2016). "Next, the effect of overexpressed PPP2R1A on tumor growth was evaluated in a xenograft model." (PMID 27272709, 2016). "Moreover, we found that PPP2R1A expression can influence the tumor microenvironment by regulating immune cell infiltration, particularly by potentially promoting an M2-like macrophage polarization and Treg recruitment, thereby contributing to an immunosuppressive milieu." (PMID 41409293, 2025). "Moreover, the median survival time and the univariate Cox regression hazard ratio of patients with PPP2R1A-mutated tumours were much better than those of patients with PPP2R1A-non-mutated tumours." (PMID 34911954, 2021). "Protein phosphatase 2 regulatory subunit A alpha (PPP2R1A) is the most common scaffold protein in the PP2A complex and has known tumor-suppressive functions." (PMID 40251453, 2025). "Since PPP2R1A is an important component of PP2A that can dephosphorylate Akt and mitogen-activated protein kinase and play tumor-suppressive roles, we performed a rescue experiment to determine the role of NET-PPP2R1A-modulated PPP2R1A in this study." (PMID 37156838, 2023). "As the scaffold protein of PP2A, the regulation of the PPP2R1A protein level is closely related to the function of PP2A, which plays tumor suppressive roles." (PMID 37156838, 2023).
tumor (continued). "PPP2R1A, a subunit of Ser/Thr protein phosphatase 2A (PP2A), has been found to act as a tumor suppressor." (PMID 36292952, 2022). "PPP2R1A, an isoform of PP2A, is an important serine/threonine protein phosphatase and is considered to be a tumor suppressor in some human malignancies." (PMID 34076143, 2021). "We compared the expression level of STRIPAK genes between normal tissue and tumor tissue via GEPIA2, discovered that only PPP2R1A were observed significant difference." (PMID 32754603, 2020). "There were significantly comparable methylation levels of PPP2R1A and TRAF3IP3 between normal and tumor tissue." (PMID 32754603, 2020). "Overexpression of PPP2R1A could maintain high levels of BCL-XL expression by stabilizing the PRPF1 complex, thereby inhibiting tumor cell apoptosis." (PMID 41409293, 2025). "Additionally, the phosphorylation of Tyr261 in PPP2R1A enhances the activity of PP2A, leading to the dephosphorylation of IMPDH2, thereby promoting S-phase progression and tumor growth downstream of the FGFR signaling pathway." (PMID 40251453, 2025). "Our analysis revealed a significant negative correlation (r = -0.5090) between PPP2R1A protein abundance and mRNA expression in tumor and adjacent non-tumor tissues." (PMID 41409293, 2025). "Compared with treatment with LB100 or anti-PD1 alone, the combination of LB100 and anti-PD1 synergistically improved its activity on anti-tumour growth and increased survival, although the synergistic effect of LB100 and anti-PD1 was less than that of Ppp2r1a knockdown and anti-PD1." (PMID 34911954, 2021). "To demonstrate that Ppp2r1a knockdown converted cold tumours into hot tumours by increasing neoantigen, we submitted the RNA-seq data of CT26-shppp2r1a and CT26-scr tumour samples, integrated in the fastq.gz files, and applied the NAP-CNB29 to predict neoantigens." (PMID 34911954, 2021). "Notably, analysis of the independent CPTAC dataset revealed a contrasting pattern, with both PPP2R1A protein (TMT log2 ratio) and mRNA (gene expression count) levels being significantly lower in LUAD tumor tissues compared to adjacent normal tissues (P < 0.001)." (PMID 41409293, 2025). "Similarly, it has been shown that HRSL3, a tumor suppressor gene, interacts with the scaffold subunit PPP2R1A, but not with the catalytic one20." (PMID 27611305, 2016). "Ppp2r1a knockdown did not affect CT26 growth in syngeneic animals in the presence of control antibodies, however inhibited tumour growth in the presence of anti-PD1, compared to cells transfected with control shRNAs (WT CT26)." (PMID 34911954, 2021). "The promoter methylation level of PPP2R1A was not parallel to the expression level, lower methylation were observed in LIHC tumor tissues while the expression level is higher." (PMID 32754603, 2020).